KRAS (KRas proto-oncogene, GTPase)
Diseases named in the same sentence as KRAS in open-access papers (continued):
Sharing a sentence is not in itself a finding about the gene and the disease.
cancer (continued). "Forty-six cancers revealed concordance of KRAS mutation status: 27 contained mutated KRAS and 19 had only wild KRAS." (PMID 30368666, 2019). "Several studies reported that MSS CRCs, associated with BRAF mutations, show higher mortality and decreased overall survival with respect to both MSI/BRAF mutated and MSS/KRAS mutated cancers." (PMID 31330830, 2019). "Elevated gene expression of YAP is associated with cancer relapse in KRAS-driven colon and pancreatic cancers." (PMID 30805310, 2019). "Mutations in KRAS have been identified in many human cancers and result in the constitutive activation of KRAS and the receptor tyrosine kinase (RTK) pathway." (PMID 31111275, 2019). "Despite the presence of a mutation in KRAS gene codon 12, GEO cancer cells are very sensitive to cetuximab treatment with an IC50 of 0.1 μg/mL." (PMID 31557914, 2019). "Alterations of the KRAS gene are typically missense mutations that can lead to the oncogenic conversion of KRAS resulting in the constitutive activation of its effector pathways and thus cancer development and progression." (PMID 31600989, 2019). "In human cancer cell lines carrying KRAS mutations and cells ectopically expressing oncogenic H‐Ras, autophagy is induced after the extracellular matrix is isolated." (PMID 30984540, 2019). "In fact, RAS is the most frequently mutated oncogene in human cancer, with mutation in the KRAS isoform the most commonly found." (PMID 31847096, 2019). "In agreement with previous observations 17, all the cancer associated exon-cassette events were skipped, including ES events in KRAS and RHOT1, indicating protein feature losses or changes that was frequently observed in cancer progression." (PMID 31695792, 2019). "That study found that mutated KRAS caused Asp decrease and Asn increase and that these changes were associated, both in cancer cell lines and primary tumors, with increased ASNS expression through the PI3K-AKT-mTOR pathway." (PMID 31998641, 2019). "Consistent with this, KRAS proximity to EGFR and its canonical downstream kinases, Raf1 and PI3K P110α decreased with SNARE TKO and increased with SNORD50A/B KO in cancer cells with activating oncogenic KRAS mutations." (PMID 31712554, 2019). "The larger numbers of the three cancer types in the MSK-IMPACT cohort are consistent with a higher number of KRAS G12D, G12V, and G12C variants observed in the MSK-IMPACT cohort." (PMID 31796730, 2019). "In four cases (#1, #3, #5, and #6), the same KRAS mutations were present in both the primary and the matched recurrent cancer." (PMID 30467323, 2019). "Intriguingly, a mutation of K117 in KRAS (K117 N) has been found in cancer patients, indicating that K117 should be an important site in KRAS for regulation of its activity." (PMID 30971271, 2019). "Of these, KRAS is the most mutated (86% of all RAS-mutant cancers), followed by NRAS (12%), and HRAS (4%)." (PMID 31681587, 2019). "KRAS’s role in cancer is caused by specific point mutations in its guanosine triphosphate-binding domain, which make it constantly active and therefore a deregulated signal transducer for proto-oncogenic pathways." (PMID 31379928, 2019). "For this, we selected KRAS mutations because all three CRC patients had KRAS mutations, which are among the most important driver mutations in many cancers, including CRC." (PMID 31896242, 2019).
cancer (continued). "In this context it should be recognized that the cancer cells differ in their mutation status; notably the BxPC-3 cell line is the only one with wild type KRAS." (PMID 31208372, 2019). "Due to the difficulties in detecting cancer-specific mutations at the early disease stage, we developed a novel approach to specifically enrich mutant KRAS alleles in ctDNA using biotinylated pyrrole–imidazole (PI) polyamides." (PMID 31383871, 2019). "The high incidence of RAS isoforms—HRAS, NRAS, and KRAS—mutations in human cancer and its associated relevance in this disease has long been known and explored." (PMID 31847096, 2019). "Activating mutations in RAS are among the most common oncogenic drivers in human cancers, with KRAS being the most frequently mutated oncogene." (PMID 31332011, 2019). "Our model provides a robust platform to study the intricacies of oncogenic KRAS mutation that complicates cancers like that of the colon." (PMID 31766149, 2019). "For instance, gene abnormalities in KRAS, one of the most frequently mutated oncogenes in human cancers, alter cellular glucose uptake, glycolytic flux, and glutamine usage." (PMID 31221965, 2019). "In summary, the example of patient-derived, recurrent somatic synonymous mutations in codon 12 of KRAS documents the potential impact of synonymous mutations on cancer protein expression." (PMID 31189880, 2019). "Meanwhile, studies by our and other groups suggested that targeting PDE6D-KRAS interaction is an effective approach to tackle both KRAS wild type and -mutated cancer types." (PMID 30901922, 2019). "The functional consequences of these two KRAS mutations are yet to be evaluated, although the Catalogue of Somatic Mutations in Cancer database (COSMIC db) gives them a FATHMM prediction score of 0.98, thus classifying them as both deleterious and pathogenic." (PMID 31816869, 2019). "Induction of biallelic APC loss and heterozygous KRAS mutation in our mice led to the development of cancers in the proximal colon including the cecum." (PMID 31766149, 2019). "Afterwards, the cancer tissues were divided in two subgroups: CRC with mutation in KRAS gene and CRC with wildtype KRAS gene." (PMID 31673240, 2019). "Because distinct mutations can shift the ensemble in different ways, the resulting edges can precipitate altered types of cancer by the same protein, as in the case of KRas driver mutations, which have different frequencies in distinct cancers." (PMID 31220071, 2019). "These suggest that KRAS mutations at codon 12 are widespread over the whole cancer tissue and probably, inhomogeneous distribution of KRAS point mutation in NSCLC is relatively rare (5/32 of studied KRAS mutation positive tumors)." (PMID 30368666, 2019). "These genetic mutations implicate pathways often dysregulated in cancer, including KRAS, TGFβ, WNT, NOTCH, ROBO/SLT, G1/S, SWI-SNF, and chromatin/DNA/RNA modification and repair." (PMID 31703358, 2019). "DMF has been shown to be cytotoxic in patient and mouse derived cancer cell lines from lung and colon adenocarcinoma with KRAS mutations, likely via effect on decreasing activity of the Nrf2/DJ-1 antioxidant pathway and contributing to cancer cell death." (PMID 31998289, 2019). "Since KRAS mutations are among the most common cancer drivers, ddPCR assays designed to detect them are commercially available, and the development of multiplex ddPCR assays against them has been reported." (PMID 31477768, 2019). "KRAS G12C is rarely mutated in KRAS-addicted cancers and it is likely that KRAS G12D and G12V, the most common mutant KRAS alleles, will be more challenging to specifically inhibit." (PMID 31681587, 2019). "On the other hand, although the role of TRAIL in cancer immunosurveillance has been always described as protective, recently, a study describing how endogenous TRAIL/TRAIL-R signaling promotes migration and invasion of KRAS-mutated cancers has been reported." (PMID 30934872, 2019).
cancer (continued). "The rs712 polymorphism in a let-7 microRNA-binding site at KRAS gene has been associated with cancer." (PMID 31156795, 2019). "Because cancer, particularly solid tumors, is a heterogeneous disease involving disparate aberrant mutations, such as KRAS and BRAF mutations, predicting clinical outcome from a few mutations is difficult." (PMID 31208461, 2019). "About one-third of all human cancers exhibit oncogenic mutations in RAS isoforms (KRAS, NRAS, and HRAS) making Ras an important anti-cancer target." (PMID 31856761, 2019). "We decided to focus on hotspot mutations in the proto-oncogene KRAS, which are shared at high frequencies across multiple cancers histologies." (PMID 30683863, 2019). "In 11 EBC samples obtained from the remaining subgroup of 12 KRAS mutation positive NSCLC patients’ samples the same mutated sequence was observed as in the cancer tissue." (PMID 30368666, 2019). "Since KRAS is the most frequently mutated oncogene in a wide variety of cancers, the findings of this investigation are likely to be of broad interest and have a large scientific impact." (PMID 31635338, 2019). "One other smaller study which adjusted for mucinous type and location only investigated methylation in ELMO1 along with other epigenetic markers in a panel and found worse prognosis in KRAS mutated cancers." (PMID 31340858, 2019). "Intratumor heterogeneity and inhomogeneous distribution of KRAS point mutation in codon 12 in cancer tissue can occur in NSCLCs." (PMID 30368666, 2019). "This problem is particularly at the forefront for KRas, and especially its KRas4B splice variant, the most highly oncogenic Ras isoform in human cancers." (PMID 30921324, 2019). "Here, an integrated approach to natural product screening is proposed, which uncovered eight new natural product scaffolds for KRAS—the most frequently mutated oncogenic driver in human cancers, which has remained thus far undrugged." (PMID 31231840, 2019). "Mutations in the three major Ras isoforms, HRAS, NRAS, and KRAS, which impair GTPase activity and/or the ability of Ras to interact with negative regulators are found in approximately a third of human cancers." (PMID 31497244, 2019). "Cells at the invasive front frequently exhibited higher ERK phosphorylation levels compared with cells in central areas of the same cancer, and CRCs with activating KRAS mutations also showed heterogeneous ERK activity." (PMID 31266962, 2019). "As a major isoform of RAS, KRAS mutations are frequently found in many cancers, including pancreatic, colon, and lung cancers." (PMID 30674639, 2019). "Cetuximab was originally approved for mCRC in 2004, though later experiments showed that the presence of KRAS mutation in cancer cells bestows resistance to cetuximab." (PMID 31366129, 2019). "The cell-free DNA released from NSCLC and DNA from circulating cancer cells can contribute to high ratio of positive results of KRAS mutation in the whole blood samples." (PMID 30368666, 2019). "There was a high accordance between KRAS mutation status in EBC–DNA and cancer tissue in NSCLC patients what suggests usefulness of monitoring KRAS mutation in EBC–DNA as a biomarker of NSCLC." (PMID 30368666, 2019).
cancer (continued). "Mutations in KRAS gene are cancer-driven genetic events that are often seen in pancreatic ductal adenocarcinoma (90%), lung, and colon cancers (30–40%)." (PMID 31881642, 2019). "For example, it has been shown that the pro-oxidative properties of vitamin C (ascorbate in the reduced form) selectively kill cancer cells with KRAS pathway mutations in a ROS-dependent manner." (PMID 31288436, 2019). "In contrast, mutant larvae developed enlarged livers when induced with liver specific expression of KrasG12V, one of the common mutations of KRAS that leads to cancer in humans." (PMID 31208154, 2019). "The small GTPase KRAS, which is frequently mutated in human cancers, must be localized to the plasma membrane (PM) for biological activity." (PMID 31451509, 2019). "The concordance ratios of KRAS sequences were 11/12 and 5/12 (p = 0.03) between EBC and cancer tissue, and blood and cancer tissue, respectively, in the subgroup of 12 KRAS-mutation positive NSCLC patients." (PMID 30368666, 2019). "We also revealed that aberrant Wnt/β-catenin signaling activates cancer stem cells when oncogenic KRAS mutations is present in colorectal cancer." (PMID 30679620, 2019). "As BRAF and RAS mutations, especially KRAS, broadly occur in cancers, it will be of interest to systematically analyze the relationship between UHRF1/DNMT1 expression and BRAF/RAS mutations." (PMID 30696879, 2019). "These mutations are found in 27% of all human cancer, and KRAS is most commonly affected in pancreatic (with around 90%), colon (40%), and lung (25%) adenocarcinoma." (PMID 31861875, 2019). "Mutations in either variant renders them oncogenic, and in human cancers, variant 4a often becomes the more widely expressed KRAS transcript." (PMID 31009485, 2019). "In a recent study, CRISPR-Cas9 was applied to cancer cells caused using KRAS mutations, which resulted in the repression of the proliferation of cancer cells and a gradual decrease of the tumor burden caused by cancer cells." (PMID 31877894, 2019). "Remarkably, the TCGA database indicates that both FBXW7 and SLC9A3 are commonly co-mutated with KRAS in human cancers." (PMID 31748650, 2019). "There are many such molecules, and a good example is the KRAS gene, which encodes a small GTPase and is the most common locus for gain-of-function mutations and/or activation of oncogenic activity in human cancers by a single amino acid substitution." (PMID 31798960, 2019). "We found that intratumor heterogeneity of KRAS point mutation at codon 12 and inhomogeneous distribution of this mutation over the cancer tissue can occur in NSCLCs." (PMID 30368666, 2019). "In 3D cultures, Caco-2 cells transfected with mutated KRAS or BRAF formed multicellular structures analogous to anoikis-resistant subpopulations in actual carcinomas, and serve as an in vitro model for anoikis resistance." (PMID 31545494, 2019). "Mutations in KRAS were prevalent in mixed (1/3, 33.3%) and endometrioid (1/5, 20.0%) carcinomas, less frequent in serous samples (4/64, 6.2%), and an exclusive event in the clear cell tumor sample (1/1, 100.0%)." (PMID 31197119, 2019). "As a critical molecular mechanism of CRCs, CIMP-H carcinomas exhibit abnormal Wnt/β-catenin pathway signalling and KRAS mutations, which represent an essential conventional adenocarcinoma sequence in CRCs." (PMID 31412872, 2019). "A recent study from Taiwan also confirmed the KRAS mutation as an important factor in the ovarian mucinous adenoma-borderline tumor-carcinoma sequence." (PMID 31030485, 2019). "This is of interest as KRAS mutation is the most frequent mutation type and present in 45% of serrated carcinomas." (PMID 31545494, 2019).
cancer (continued). "Some forms of cancer, like pancreatic cancer, present late and are difficult therefore to treat but these contain a high proportion of KRAS mutations and are thus potentially susceptible to RAS-binding drugs." (PMID 29989546, 2018). "Indel-associated disruption of the mutant KRAS alleles correlated with reduced viability of the cancer cells." (PMID 30089886, 2018). "RAS genes are mutated in different frequencies, KRAS being mutated in 85% of all RAS-driven cancers, NRAS in 12% and HRAS in 3% (COSMIC v82)." (PMID 29455659, 2018). "Taken together, only KRAS amplification of LUAD cancer type showed strong association with expression of both K-Ras isoforms (r2 > 0.9), although S value was less than 0.6 for K-Ras4B expression." (PMID 29504894, 2018). "In contrast, the puromycin selection procedure reduced viability of all cancer cells lines following the CRISPR/Cas9-mediated targeting of the respective KRAS mutations to less than 10%." (PMID 30089886, 2018). "Taken together, the NGS and MTT assay results suggested that the Cas9 nuclease can be used to distinguish between specific KRAS oncogene variants and used to selectively inhibit the growth of specific cancer cell lines." (PMID 30089886, 2018). "Despite the knowledge acquired over the past years and the new therapeutic technologies, treating KRAS-mutated cancers still remains a major health issue." (PMID 29721157, 2018). "Clinically, KRas, the most frequently mutated Ras gene, confers resistance to therapy in cancers such as pancreatic, colon, and lung." (PMID 30514931, 2018). "Current immunoassay validations have highlighted the design and potential development of mimotope 164-D against G13D KRAS(+) variants as a cancer vaccine candidate." (PMID 30042874, 2018). "Lentiviral transduction of Cas9 and the sgRNAs into cancer cells with respective KRAS mutations resulted in high frequency of indels in the seed region." (PMID 30089886, 2018). "First, to perceive up-to-date data of KRAS G12X missense mutation frequencies, we compiled data from the Catalogue of Somatic Mutations in Cancer." (PMID 30199525, 2018). "In this study, we developed a method to impair cancer cell proliferation by directly targeting two specific mutations at codon-12 of the KRAS oncogene." (PMID 30089886, 2018). "This genetics-driven process echoes the KRAS mutation in providing cancer cells a propagation advantage in a hypoglycemic microenvironment." (PMID 30131529, 2018). "We reasoned that because mutated KRAS is crucial for cancer proliferation pathways, indels introduced into the gene via error-prone NHEJ would be detrimental to the survival of the cancer cells." (PMID 30089886, 2018). "Despite these slight differences, the overall efficacy of BET inhibition in these two models indicates that this can represent an effective therapeutic approach against both KRAS-mutated cancers." (PMID 29721157, 2018). "This study provides detailed insights into the novel cytotoxic mechanism of an anti-cancer compound from an herbal plant and promotes the anti-cancer potential of krukovine in NSCLC with KRAS mutation." (PMID 30186180, 2018). "Our study suggests an important role of GOT1 to coordinate the glycolytic and the oxidative phosphorylation pathways in KRAS mutated cancer cells." (PMID 29751795, 2018). "This variant allele caused the disruption of let-7e-mediated regulation of KRAS and the consequent upregulation of KRAS expression correlating with increased cancer risk." (PMID 29419779, 2018). "In this work, the In-check platform was validated to assess the mutational status of KRAS oncogene, the main factor responsible for the development of different cancers, in particular CRC, giving them resistance to anti-EGFR therapies." (PMID 29304017, 2018).